PRDX1 (peroxiredoxin 1)
Diseases named in the same sentence as PRDX1 in open-access papers (continued):
Sharing a sentence is not in itself a finding about the gene and the disease.
hepatocellular carcinoma (23 papers, 2008 to 2026). A malignant tumor that arises from hepatocytes. "Collectively, mounting evidence identifies STMN1 and PRDX1 as potential biomarkers for hepatocellular carcinoma (HCC), further establishing their association with ferroptosis." (PMID 41403955, 2025). "In this study, using human hepatocellular carcinoma HepG2 cells as an in vitro model, we identify ginsenoside Rg5 (Rg5) as a previously unrecognized small-molecule inhibitor of PRDX1." (PMID 41683534, 2026). "Our study particularly emphasizes the function of STMN1 and PRDX1 as key drivers in hepatocellular carcinoma progression." (PMID 41403955, 2025). "Concurrently, research demonstrates that PRDX1 promotes hepatocellular carcinoma development through suppression of the intrinsic mitochondrial apoptosis pathway." (PMID 41403955, 2025). "The levels of GPx1 and 2 and Prdx1, 3, and 5 in hepatoma cells were increased compared to hepatocyte-like cells, while GPx3 was markedly reduced." (PMID 37189460, 2023). "In the present study, we found that PRDX1 expression levels were significantly upregulated in hepatocellular carcinoma cell lines, especially in HEPG2 cells." (PMID 35705729, 2022). "The PRDX1 has been verified to be involved in the regulation of NK cells and protective autophagy in hepatocellular carcinoma." (PMID 35401932, 2022). "PRDX1 is the hub gene of the prognosis model and has a high expression in hepatocellular carcinoma tumor tissue and cell lines." (PMID 35705729, 2022). "It has been shown that decreased PRDX1 levels lead to impaired antioxidant response and excessive accumulation of ROS, promoting hepatocellular carcinoma cell death." (PMID 35705729, 2022). "And we selected PRDX1 as the key which silencing can promoted ferroptosis in hepatocellular carcinoma according to the experimental validation." (PMID 35705729, 2022). "Genistein is a flavonoid that induces apoptosis in human hepatocellular carcinoma SNU 449 cells via downregulation of peroxiredoxin-1." (PMID 30917517, 2019). "ALDH2, ITGB2, LGALS3, CTSB, PRDX1, and CD14 were identified as multifunctional proteins that are associated with tumorigenesis, damage, cancer cell death, necrosis, fibrosis, hepatocellular carcinoma, steatosis, and inflammation." (PMID 29481576, 2018). "Recently, some studies showed that the PRDX1 was overexpressed in various human tumors such as breast, lung, urinary, and hepatocellular carcinoma, and its interaction with toll-like receptor 4 (TLR4) stimulates tumor angiogenesis in prostatic carcinoma." (PMID 27362486, 2016). "Homozygote Prdx1−/− mice knockouts develop hemolytic anemia and several malignant cancers including epithelial and mesenchymal tumors such as hepatocellular carcinoma, fibrosarcoma, osteosarcoma, islet cell adenomas, and adenocarcinomas of the lung and breast." (PMID 22347400, 2012). "The expression of PRDX1 was obviously reduced in hepatic carcinoma cells treated with Tc3." (PMID 39816682, 2025). "In addition, the knockdown of PRDX1 partially rescued the hepatic carcinoma cell death rate and LDH release induced by Tc3." (PMID 39816682, 2025). "Therefore, PRDX1 can be used as a potential biomarker for the prognostic value of hepatocellular carcinoma and can serve as a therapeutic target for hepatocellular carcinoma." (PMID 35705729, 2022). "Thus, our results suggest that silencing PRDX1 promotes ferroptosis in hepatocellular carcinoma cells." (PMID 35705729, 2022). "Similarly, knockdown of Prdx1 by siRNA increased hepatitis B virus propagation in human hepatoma Hep38.7-Tet cells." (PMID 34681144, 2021). "UHRF2 enhances autophagy and oncogenic traits in hepatocellular carcinoma (HCC) by interacting with PRDX1 and PARP1, suggesting its potential as a biomarker and therapeutic target for HCC." (PMID 39315094, 2024).
hepatocellular carcinoma (continued). "Furthermore, high PRDX1 expression was associated with poor prognosis of hepatocellular carcinoma, and silencing PRDX1 increased the accumulation of Fe2+ and led to lipid peroxidation accumulation in hepatocellular carcinoma cells, which promoted ferroptosis in hepatocellular carcinoma." (PMID 35705729, 2022). "Meanwhile, there is also a large body of research demonstrating that overexpression of PRDX1 is a significant indicator of poor prognosis in non-small cell lung cancer, hilar cholangiocarcinoma, oral squamous cell carcinoma, pancreatic cancer, hepatocellular carcinoma, and rectal cancer." (PMID 30104402, 2018). "To elucidate the functional role of PRDX1 in HCC progression, we assessed its effects on cell proliferation, migration, invasion, and apoptosis in Huh7 hepatocellular carcinoma cells." (PMID 40693141, 2025). "We further found that silencing PRDX1 increased the accumulation of ferrous ions and lipid peroxidation accumulation in HEPG2 cells and promoted ferroptosis in hepatocellular carcinoma." (PMID 35705729, 2022). "To determine the clinical relevance of PRDX1 expression levels, we examined PRDX1 expression in a normal liver cell (LX2) and three hepatocellular carcinoma cell lines (MHCC-97H, HEPG2, and Huh-7)." (PMID 35705729, 2022). "Interestingly, women with hepatocellular carcinoma (HCC) exhibit elevated expression of Prdx3, whereas men—of Prdx1." (PMID 34207367, 2021). "Upregulation of GPX4, PRDX1 and CYP19A1 genes have been previously detected in biopsies of HCV infected chimpanzees or in human hepatocellular carcinoma (HCC) samples." (PMID 18793431, 2008).
prostate carcinoma (21 papers, 2010 to 2026). A carcinoma that arises from epithelial cells of the prostate gland. "PRDX1 (Peroxiredoxin 1) is a widely expressed peroxidase, and in prostate cancer, HJURP may inhibit tumor cell sensitivity to iron mutation inducers via the PRDX1 pathway." (PMID 41523581, 2026). "PRDX1 is also associated with tumor invasiveness, metastasis, and chemotherapy resistance in gastric cancer (GC) and other cancers such as pancreatic cancer (PC), ovarian cancer (OC), and prostate cancer (PCa), emphasising its essential biological function across various malignancies." (PMID 40256656, 2025). "Recent studies have reported increased expression of PRDX1 in several human cancers, including breast, esophageal, lung, and prostate cancers." (PMID 40645965, 2025). "Both peroxiredoxin 1 (PRDX 1) and peroxiredoxin 3 (PRDX 3) proteins were significant and their overexpression in prostate cancer has been proposed to be linked to cancer initiation and progression." (PMID 37627612, 2023). "It is important to notice that associations with PRDX1 and the endocrine system have been recently described in prostate cancer, including effects of PRDX1 on androgen receptor activity and the response to anti-androgen therapies." (PMID 25011585, 2014). "In prostate cancer, reduction in Prdx1 expression was found to lead to reduced tumor vasculature formation, and further inhibition of tumor growth." (PMID 24009050, 2013). "This review covers the possible roles of two ROS-induced transcription factors, Nrf1 and Nrf2, and the antioxidant proteins peroxiredoxin-1 (Prx-1) and Thioredoxin-1 (Txn-1) in modulating AR expression and signaling in aggressive prostate cancer (PCa) cells." (PMID 24281119, 2010). "In prostate cancer, excessive ROS induce NFE2L1 activation and regulate downstream antioxidant genes, such as peroxiredoxin 1 (Prx-1) and thioredoxin 1 (Txn-1), which compensate for oxidative stress and maintain redox homeostasis." (PMID 39061827, 2024). "PRDX1 is a member of the peroxiredoxin family that is nonclassically secreted from cells and acts as a mediator of inflammation in prostate cancer." (PMID 25024510, 2014).
liver cancer (15 papers, 2013 to 2026). An epithelial or non-epithelial malignant neoplasm that arises from the liver. "The PRDX1 gene encodes a member of the peroxiredoxin family of antioxidant enzymes and can inhibit the mitochondrial apoptosis in liver cancer, accelerating its progression." (PMID 39000203, 2024). "At day 5, one (A1AG) of the upregulated proteins and four (ENOA, F16P1, PEPD and PRDX1) of the downregulated proteins were reported to be associated with liver cancer." (PMID 32095334, 2020). "Consequently, high PRDX1 expression in liver cancer could serve as a diagnostic marker for liver cancer and is linked to poor prognosis, corroborating the findings of bioinformatics." (PMID 37781072, 2023). "There is such a relationship between STMN1 gene and liver cancer, while PRDX1 is most correlated with endometrial cancer." (PMID 41403955, 2025). "PRDX1 was downregulated to verify its role in ferroptosis, and it was found that downregulating PRDX1 can promote ferroptosis, illustrating that PRDX1 can be used as a prognostic marker for liver cancer." (PMID 38200525, 2024). "A prognostic model with PRDX1 as the central gene was established, and it was found that it was highly expressed in liver cancer; especially in HepG2 cells, as an important antioxidant protein." (PMID 38200525, 2024). "Various studies reveal high PRDX1 expression in liver cancer, indicating an inverse correlation with the prognosis of HCC patients." (PMID 37781072, 2023). "The heightened PRDX1 expression in gastric cancer 48, 51 and liver cancer 57, 60 is consistent with the box-plot results." (PMID 37781072, 2023). "Intriguingly, only in liver cancer does the high expression of PRDX1 significantly reduce patient survival time, with the difference deemed statistically significant (p<0.05)." (PMID 37781072, 2023). "Multiple studies have shown that Prdx1 is involved in the progression of human liver cancer, including tumor angiogenesis, apoptosis, autophagy, and poor patient prognosis in HCC." (PMID 35875077, 2022). "At days 3 and 5, six proteins (LG3BP, A1AG, ENOA, F16P1, PEPD and PRDX1) were related to liver cancer and other diseases." (PMID 32095334, 2020). "Fructose-1, 6-bisphosphatase 1 (F16P1) and peroxiredoxin 1(PRDX1) were considered as potential biomarkers for the prognosis of liver cancer." (PMID 32095334, 2020). "The amounts of three key proteins in the TXN system, TXNRD1, TXN, and peroxiredoxin 1 (PRDX1), in tumor and surrounding normal tissue samples from the three lung and three liver cancer patients were examined in duplicate by western blotting." (PMID 26569310, 2015). "Collectively, these findings suggest that PRDX1 inhibition may represent a broadly exploitable vulnerability in liver cancer and establish Rg5 as a promising candidate for developing targeted and combinatorial therapies against HCC." (PMID 41683534, 2026). "Additionally, we found that PRDX1 was ubiquitously highly expressed in multiple liver cancer cell lines." (PMID 37842089, 2023). "This suggests that PRDX1 might hold greater significance in liver cancer." (PMID 37781072, 2023). "Interestingly, high PRDX1 expression only decreased the survival time in liver cancer patients." (PMID 37781072, 2023). "Among the 28 unique proteins of the liver tumour model, five proteins have been reported to be associated with liver cancer, including serum amyloid P component (SAMP), alpha-l-fucosidase (AFU), urokinase-type plasminogen activator (UROK), peroxiredoxin 6 (PRDX6), and peroxiredoxin 1 (PRDX1)." (PMID 32095334, 2020). "Peroxiredoxin 1 (PRDX1), a NRF2 target gene, is known to act as an oxidative stress sensor and promote liver cancer growth." (PMID 32751080, 2020). "In liver cancer (HCC), PRDX1 promotes cancer cell survival by reducing ROS accumulation and may exacerbate tumor progression by influencing immune evasion mechanisms." (PMID 40256656, 2025).
liver cancer (continued). "Nevertheless, elevated PRDX1 levels only significantly diminished the survival time of liver cancer patients, exerting no statistically significant impact on the survival duration of patients afflicted by the other three types of gastrointestinal cancers." (PMID 37781072, 2023). "Consequently, PRDX1 may serve as a potential biomarker for HCC detection and prognosis, and its inhibitors could be candidate drugs for liver cancer treatment 57-61." (PMID 37781072, 2023).
pancreatic cancer (15 papers, 2017 to 2025). "Determining the timing of Prdx1 and/or Txn secretion during neoplasia could be a valuable diagnostic tool when used in combination with pancreatic cancer markers such as CA19-9." (PMID 29190947, 2017). "In addition, PRDX1 associates with the formation of membrane protrusions through modulation of the activity of p38MAPK, which in turn promotes pancreatic cancer cell invasion." (PMID 27653015, 2017). "We hypothesize that accumulation of these post-translational modifications and non-redox associated functions as lesions progress leads to the eventual secretion of Prdx1, which is associated with a worse prognosis in pancreatic cancer." (PMID 29190947, 2017). "Supplementing obese animals with SAM sensitized pancreatic tumors to chemotherapy, and treating pancreatic cancer cells with queuosine increased PRDX1 expression." (PMID 39024520, 2024). "PRDX1, has been identified as a biomarker helpful in the diagnosis of several diseases, including ovarian cancer, abdominal aortic aneurysm, pancreatic cancer, and irritable bowel syndrome." (PMID 38825675, 2024). "In pancreatic cancer, there is a significant elevation in PRDX1 expression levels, making it a viable therapeutic target." (PMID 37781072, 2023). "Some studies indicate a close relationship between PRDX1 and other gastrointestinal cancers such as pancreatic cancer 74, cholangiocarcinoma 75, and oral cancer." (PMID 37781072, 2023). "To study if chemoresistance in the presence of Q was via induction of PRDX1, we next inhibited PRDX1 using siRNA in pancreatic cancer cells SU86.86 and determined effect on cell viability in the presence of paclitaxel ± Q. Silencing was verified by qPCR." (PMID 35816618, 2022). "This study shows for the first time that microbial metabolites like Queuosine contribute to therapy resistance in pancreatic cancer under conditions of obesity by upregulating PRDX1, which protects them from chemotherapy induced oxidative stress." (PMID 35816618, 2022). "Treatment of pancreatic cancer cells with Q increased PRDX1 involved in oxidative stress protection." (PMID 35816618, 2022). "We observed that upon silencing Prdx1 in pancreatic cancer cells (MIA-PACA2), queuosine was unable to protect the cells from paclitaxel induced cell death." (PMID 35816618, 2022). "Our results showed that Q preferentially induced the expression of PRDX1 in pancreatic cancer cells SU86.86 and MIA-PACA2." (PMID 35816618, 2022). "In support of these previous results, we found that Peroxiredoxin-1 mRNA was significantly upregulated in human pancreatic tumors and that its high expression correlated with shortened patient survival." (PMID 33917763, 2021). "The levels of PRDX1 expression are significantly increased in pancreatic cancer compared to normal tissues, and this overexpression is closely related to tumour angiogenesis." (PMID 27653015, 2017). "We found that overall Prdx1 expression was elevated in tumor tissue as compared to adjacent normal tissue in a pancreatic cancer patient tumor array (n=60)." (PMID 29190947, 2017). "Kras associated changes in the expression or function of Txn and Srxn throughout pancreatic tumorigenesis will therefore have a significant effect on Prdx1 signaling in pancreatic cancer." (PMID 29190947, 2017). "Increased Prdx1 expression in pancreatic cancer patient serum and tissue correlates with decreased overall and relapse-free survival and elevated VEGF expression." (PMID 29190947, 2017). "We would like to acknowledge Leslie Poole for her assistance in understanding mechanisms of Prdx1 signaling in this manuscript and the Hirshberg Foundation for Pancreatic Cancer Research for support related to the TMA and its analysis." (PMID 29190947, 2017). "Deciphering the mechanisms that designate the conditions in which Prdx1 functions as a peroxidase, a chaperone, or an inflammatory factor will be essential to understanding its role in pancreatic cancer." (PMID 29190947, 2017).
pancreatic cancer (continued). "Understanding the mechanisms that regulate Prdx1 nuclear localization and/or secretion throughout pancreatic tumorigenesis will be essential to determining its role in pancreatic cancer aggressiveness and patient survival." (PMID 29190947, 2017). "Peroxiredoxin-1 (Prdx1) is elevated in pancreatic cancer patient tissue and serum and correlates with worse survival." (PMID 29190947, 2017). "However, there was a significant correlation between high expression of PRDX1 and poor overall survival in pancreatic cancer (Logrank P = 0.024), indicating that PRDX1 is an independent prognostic factor in cancer progression." (PMID 39430237, 2024). "Also, since silencing PRDX1 sensitized the pancreatic cancer cells to paclitaxel even in the presence of Pre-Q indicated that Q induced chemoresistance was being mediated via PRDX1." (PMID 35816618, 2022). "Results presented here demonstrate our novel observation that pancreatic cancer cells become more sensitive to Ref-1 redox inhibition when PRDX1 expression is decreased and when RelA is present in the cells indicating a novel interplay between PRDX1, Ref-1, and RelA." (PMID 35402225, 2022). "Interestingly, we observed that there are reports of mutations and copy number variation in PAIP2B, PRDX1, RNASE1, BARD1, UHMK1, and RPL3L genes associated with pancreatic cancer." (PMID 34912796, 2021). "This suggests that on a transcriptional level, Nrf1 expression may also be induced in pancreatic cancer and available to induce Prdx1 expression in pancreatic cancer." (PMID 29190947, 2017). "Interestingly, we found that Prdx1 mRNA was significantly elevated in human pancreatic cancer tissue, which correlated with increased Nrf1 mRNA expression but not with Nrf2 mRNA expression." (PMID 29190947, 2017). "We evaluated the expression of Prdx1 in human pancreatic cancer tissue." (PMID 29190947, 2017). "Future investigation of the association between these modifications and the modified localization and/or secretion of Prdx1 could also have significant implications on the prognosis of pancreatic cancer." (PMID 29190947, 2017). "This hypothesis coincides with literature that shows that high serum levels of Prdx1 are associated with a worse prognosis and elevated VEGF levels in pancreatic cancer patients." (PMID 29190947, 2017). "Silencing PRDX1 did not alter the viability of the pancreatic cancer cells." (PMID 35816618, 2022). "Using available transcriptomic datasets, we first found that Peroxiredoxin-1 gene (PRDX1) expression was significantly increased in human pancreatic tumors, but not in the other gastrointestinal cancers; its high expression correlated with shortened patient survival." (PMID 33917763, 2021).